NF1 (neurofibromin 1)
Diseases named in the same sentence as NF1 in open-access papers (continued):
Sharing a sentence is not in itself a finding about the gene and the disease.
breast cancer (continued). "Despite the emphasis of previous reports on the importance of breast cancer surveillance and follow-up in women with NF1, the efficacy and uptake of such screening programs in this patient population remains unclear." (PMID 31121919, 2019). "Early breast cancer screening guidelines need to be extended to include women with NF1." (PMID 30962859, 2019). "Nevertheless, high-risk breast cancer screening is currently recommended for all women with NF1; however, there is a lack of data regarding the feasibility and effectiveness of this screening." (PMID 31121919, 2019). "Additional evaluation on the influence of NF1 gene mutations identified in patients undergoing hereditary cancer genetic testing on breast cancer risk in individuals without clinical evidence of NF1 is needed." (PMID 30962859, 2019). "After age 50, breast cancer risk in women with NF1 does not differ significantly compared to women in the general population." (PMID 31121919, 2019). "Two hundred and eighty-six cases of NF1 and female breast cancer were identified." (PMID 30962859, 2019). "Finally, among the breast cancer predisposition genes with moderate/high-penetrance, seven genes (BMPR1A, PTEN, CDH1, NF1, RAD51C, BRIP1, and CHEK2) were replicated for Korean BRCAX (eight for Asian and 15 genes for European high-risk breast cancers)." (PMID 30323354, 2018). "The researchers also describe a newly created rat model of NF1-mutant breast cancer that they say could help further interrogate the importance of these genetic connections." (PMID 30182054, 2018). "Moreover, we identified a frequent mechanism for RAS deregulation through NF1 shallow deletion that is present in 25% of sporadic breast cancers." (PMID 30182054, 2018). "It is a logical proposition that mutations that activate RAS, like NF1 mutation, could create a tumor with a similar transcriptional phenotype as some HER2 amplified breast cancers." (PMID 30181556, 2018). "Moreover, this novel Nf1 rat model is invaluable for interrogating the role of NF1, estrogen-dependent breast cancer, and deregulated RAS signaling in sporadic and inherited breast cancer." (PMID 30182054, 2018). "So, the precise role for NF1 in breast cancer is still unclear and further studies are required." (PMID 28637487, 2017). "Inactivating NF1 mutations were also found to be associated with breast cancer severity score in oestrogen receptor-negative tumours." (PMID 28637487, 2017). "Breast cancer has been shown to be associated with NF1; however, an increased risk of breast cancer in NF1 patients has not been widely recognized or accepted." (PMID 26604930, 2015). "These authors found that the overall incidence of breast cancer in women with NF1 was 3.2%." (PMID 26604930, 2015). "Additionally, silencing the NF1 gene has been shown to confer tamoxifen resistance in human breast cancer (MCF7) cell lines." (PMID 25889501, 2015). "Loss of heterozygosity of NF1 has been detected in radiation-induced breast cancers from patients without NF1 syndrome." (PMID 25026295, 2014). "Recent studies have suggested that NF1 is a breast cancer driver gene." (PMID 25051360, 2014). "NF1 was found to be deleted in nearly all the mammary tumours from these mouse models." (PMID 25026295, 2014). "The authors suggest that there is a NF1 isoform shift in expression from type II to type I which could be important in the development and progression of sporadic breast cancer." (PMID 25051360, 2014). "However, the risk of breast cancer in patients found to have a variant in the NF1 gene without any clinical evidence is unclear." (PMID 38673061, 2024).
breast cancer (continued). "Furthermore, another study reviewed malignant neoplasms in women with NF1 and breast cancer." (PMID 38282102, 2024). "The mechanism by which NF1 mutations lead to breast cancer tumorigenesis is not well understood." (PMID 38799507, 2024). "Exactly how closely NF1 mutations predict protein loss has not been thoroughly studied using clinically relevant samples, and currently there are no protein-based NF1 diagnostics used to guide the endocrine treatment in ER+ breast cancer." (PMID 37501682, 2023). "NF1 loss-of-function mutations, RTKs mutations such as ERBB2 activating mutations, as well as alterations in other MAPK pathway genes (EGFR, KRAS, BRAF, and MAP2K1) were found to be enriched in endocrine-resistant advanced ER+ breast cancer compared to early-stage ER+ breast cancer." (PMID 38003387, 2023). "To further examine the sensitivities of NF1 deficient tumors in a more clinically relevant context, we treated a HER2 + NF1 null patient-derived xenograft (PDX) model derived from a patient with trastuzumab-refractory breast cancer with trastuzumab, trametinib, or the combination." (PMID 34795269, 2021). "Ras signaling is frequently activated in human breast cancer, usually not by mutations in a Ras gene per se, but by mutations and overexpression of upstream signaling components such as receptor tyrosine kinases and NF1 mutations." (PMID 33842308, 2021). "Furthermore, genomic data from the cBioPortal for Cancer Genomics datasets indicate that somatic NF1 mutations can be detected in a variety of malignancies, including non-small-cell lung cancer (NSCLC), ovarian cancer, breast cancer, liver cancer, and esophagogastric cancer." (PMID 33061844, 2020). "Interestingly, NF1 mutations are high in a TNBC subtype called “apocrine TNBC” with relatively high expression of androgen receptor (AR), although TNBC is overall lower in AR expression than other breast cancer subtypes." (PMID 30630526, 2019). "Multigene panel breast cancer genetic testing may identify mutations in the NF1 gene in patients not previously known to have NF1." (PMID 30962859, 2019). "Furthermore, additional studies are required to assess the influence of NF1 pathogenic variants identified in patients undergoing clinical genetic testing on breast cancer risk in individuals without clinical evidence of NF1." (PMID 30962859, 2019). "However, the risk of breast cancer in patients found to have a variant in the NF1 gene without any clinical evidence of NF1 is not clear." (PMID 30962859, 2019). "However, currently, there are no such guidelines for NF1 patients, and guidelines similar to those for Cowden syndrome, which is a genetic disorder associated with breast cancer, should be developed." (PMID 26604930, 2015). "Interestingly, around 30% of sporadic breast cancers in humans lack at least one copy of NF1 gene." (PMID 25885768, 2015). "Based on the well-established susceptibility of the Nf1 mutant background used in our models, we assessed NF1 status in radiation-induced breast cancers from survivors of HD (none having NF1) and found evidence of NF1 loss of heterozygosity, indicating that this loss occurs in human SMNs." (PMID 23565507, 2013). "For some genes, single P/LP variants were detected either only in the group of patients with breast cancer (APC, MDM1, MRE11, POLD1, NF1, RAD51C, RECQL4, and WRN) or only in the control group (MCPH1, MSH3, and XPC)." (PMID 39684352, 2024).
breast cancer (continued). "We further investigated the expression of NF1, TSC1, and TβRII in human breast cancer using the TCGA dataset." (PMID 38997291, 2024). "Of the 15 patients with NF1 incidental LPV/PV, seven (46.7%) had a personal history of breast cancer." (PMID 39539798, 2024). "In particular, while breast cancer risk does not differ significantly compared to women in the general population after the age 50, Suarez-Kelly and colleagues identified a 5-fold increased risk of developing breast cancer before the age of 50 for women with NF1." (PMID 38270845, 2024). "NF1 is a key tumor suppressor that represses both RAS and estrogen receptor-α (ER) signaling in breast cancer." (PMID 37501682, 2023). "Some of the top hits identified by our screen, including PTEN, CSK, NF1, and TSC1/2 had previously been identified by a CRISPR-Cas9 screen that was performed with the ERα+ breast cancer cell lines MCF7 and T47D." (PMID 37172090, 2023). "NF1-related tumors included malignant peripheral nerve sheath tumor, gastrointestinal adenocarcinoma, GIST, breast cancer, and pheochromocytoma." (PMID 36620543, 2022). "One female breast cancer patient tested positive for PGVs in both BRIP1 and NF1, while one patient with splenic cancer harbored PGVs in both SDHB and BUB1B." (PMID 34830767, 2021). "A trend of an increasing number of driver alterations of breast cancer-related genes was observed in recurrence samples as compared to primary tumors, including alterations in FGFR1, ESR1, NF1, BRCA1, and PTEN genes." (PMID 33059724, 2020). "Truncations and deletions in NF1 activate RAS and its downstream pathways RAF/MEK/ERK and PI3K/AKT, both of which are prominent drivers of breast cancer metastasis." (PMID 31898540, 2020). "Consequently, many cases of NF1-associated breast cancer are not diagnosed until advanced stages." (PMID 31121919, 2019). "Together, our CRISPR rat Nf1 model and our WGCNA analysis of human breast cancer confirms that NF1 is intricately connected to ER networks, including several genes that have been directly linked to endocrine resistance (i.e., FOXA1 and AR)." (PMID 30182054, 2018). "A potential mechanism for NF1 and drug resistance in breast adenocarcinoma has been suggested following analysis of the MCF-7 breast cancer cell line." (PMID 28637487, 2017). "A total of 27 patients with NF1 and nonmetastatic breast cancer treated with surgery followed by adjuvant radiation therapy between January 1995 and December 2023 were included in this study." (PMID 41487701, 2026). "This retrospective single-center study included 27 NF1 patients with nonmetastatic breast cancer treated with surgery and adjuvant radiation therapy between 1995 and 2023." (PMID 41487701, 2026). "This study represents the first clinical evaluation of adjuvant radiation therapy in patients with NF1 treated for nonmetastatic breast cancer." (PMID 41487701, 2026). "Designing tailormade interventions for young women with NF1 to enhance breast cancer awareness is therefore not viable on its own." (PMID 38859614, 2025). "A follow-up strategy for abdominal neoplasms in patients with NF1 and breast cancer has not been established." (PMID 38282102, 2024). "In GH clinic, 50 women have a diagnosis of NF1 (average age = 40.9 years), 6 (12%) of which have had a previous diagnosis of breast cancer, seven underwent breast biopsy, no breast cancer was detected in this period." (PMID 35323371, 2022).
breast cancer (continued). "While alterations of RAS/RAF/MEK/ERK genes are rare in breast cancer, ERK pathway activation may arise from alterations in upstream regulators, such as the RasGAPs NF1 and RASAL2." (PMID 36358725, 2022). "The only family history of breast cancer that was noted was in a cousin and a niece on her mother’s side, and there was no documented family history of NF1." (PMID 33842116, 2021). "For example, CDKN2A, NF1, and NBN were associated with increased risk for breast cancer in the current study, but were not significant in previously published analyses in our smaller cohorts." (PMID 31406321, 2020). "There was no reported genetic and/or clinical diagnosis of NF1 in any of the first or second-degree relatives diagnosed with breast cancer." (PMID 31121919, 2019). "Using our Nf1 rat model, human breast cancer lines, and patient-derived xenograft models, we will be able to interrogate how the presence and absence of estrogen impacts direct and indirect NF1-ER signaling." (PMID 30182054, 2018). "Our WGCNA analysis revealed an unknown network between NF1, ESR1, and RAS signaling in breast cancer." (PMID 30182054, 2018). "To determine the effect of Nf1 deficiency on RAS signaling, we examined ERK staining in normal mammary tissue, mammary epithelial cells, and mammary tumors." (PMID 30182054, 2018). "A clinician who already has an ‘explanation’ for a breast cancer in a patient with NF1 is unlikely to send off for a gene panel." (PMID 30510771, 2018). "Studies have suggested the role of the NF1 and/or the BRCA gene in the occurrence of breast cancer." (PMID 24137429, 2013). "Several of her family members were also reported to have had breast cancer but they lacked other features of NF1." (PMID 23244495, 2012). "Enrichment of NF1 binding motifs in PR binding regions in AB32 cells, but not breast cancer cells, supports this view and suggests that NF1 is a cell type-restricted PR cofactor." (PMID 22545144, 2012). "A few micro RNAs genes are present in the NF1 type-1 deletion interval: MIR4733, MIR4724, MIR193A, MIR4725, and MIR365B. miR-193a has well-known tumour suppressor functions, in hepatocellular carcinoma, endometrioid endometrial adenocarcinoma, non-small-cell lung cancer, and breast cancer." (PMID 38448973, 2024). "Our analysis suggests that PI3K inhibition may overcome the negative impact of NF1 loss in ER+, HER2− advanced breast cancers." (PMID 36892268, 2023). "Furthermore, a recent paper describes breast cancer in NF1 and shows a lack of large or whole gene deletions and an excess of nonsense and missense mutations." (PMID 31466283, 2019). "To examine whether here too, miR-10b affects c-Jun expression through RhoC and NF1, we measured their expression levels in metastatic and non-metastatic breast cancer cells." (PMID 27494896, 2016). "Despite the follow-up of patients with NF1 and breast cancer, the literature data are not clear." (PMID 24876981, 2014). "Indeed, in vitro kinase assays using purified components and 10 μM ATP showed that CRAF efficiently phosphorylates purified CDK4 at T172, whereas CDK7 and c-Jun N-terminal kinase (JNK) were excluded as relevant CAKs in the context of NF1-depleted ER+ breast cancer." (PMID 41226361, 2025). "We note that BRCA1 and NF1 were not significant in the primary cancer cohort after correction for multiple hypothesis testing, something we believe to be due to the play of chance given the wealth of data implicating these two genes in primary breast cancer." (PMID 28810143, 2017).
breast cancer (continued). "Breast cancer screening guidelines have been delineated for the general population and for women with known genetic risk factors for breast cancer (i.e. BRCA1 and PTEN syndromes) to decrease mortality through early diagnosis; however, there are currently no such guidelines for NF1 patients." (PMID 25885768, 2015). "Unexpectedly, the decreased NF1, TSC1, and TβRII expression did not clearly correlate with DMFS in the basal subtype of breast cancer patients." (PMID 38997291, 2024). "This means that more aggressive features of breast cancer, such as higher tumor grade, negative estrogen receptor, HER2 amplification, and inferior overall survival, are evident among female patients with NF1 compared to the age-matched population." (PMID 34566848, 2021).